IRS1 (insulin receptor substrate 1)
Diseases named in the same sentence as IRS1 in open-access papers (continued):
Sharing a sentence is not in itself a finding about the gene and the disease.
diabetes (continued). "This study identifies the lncRNA H19-HDAC6 axis as a significant regulator of cellular IRS1 levels and impaired levels of lncRNA H19 and HDAC6 alter IRS1 levels in the skeletal muscle during diabetes." (PMID 35842608, 2022). "RT-PCR analysis of blood RNA obtained from NS-3 treated people with T2DM for 24-weeks resulted down-regulation of gene expression in diabetes biomarkers (IRS-1, SOD-2, GCKR, IGFPB-2) compared to pre-dose values." (PMID 36540866, 2022). "Here, we present data to show that HDAC6 levels are regulated by the lncRNA H19 in the skeletal muscle during diabetes and this regulation modulates IRS1 levels, thereby exerting effects on insulin signaling." (PMID 35842608, 2022). "Induction of diabetes significantly (p < 0.05) reduced the expression of hepatic IRS-1, GLUT-4, P13K and AKT mRNA in the diabetic rats compared with normal rats." (PMID 35739183, 2022). "GSK3 inhibitors are used in the treatment of diabetes due to the down regulation of IR, IRS-1, and Akt levels." (PMID 34943997, 2021). "MAPKs play a role in the phosphorylation of serine 636/639 of IRS1 resulting in the defective activation of the PI3K by insulin in cells from patients with diabetes." (PMID 33708999, 2021). "Bouzakri and coworkers found that serine 636 phosphorylations on IRS1 were significantly higher in muscle cells from diabetes patients than in cells from control subjects." (PMID 33708999, 2021). "Metformin, a first-line therapy for type 2 diabetes mellitus, is an effective and reversible selective inhibitor of IRS1/PI3K/Akt, which affects metabolism in vivo." (PMID 34071638, 2021). "Diabetes can inhibit insulin/IRS1 signalling in mesangial and glomerular endothelial cells, probably through the protein kinase C (PKC) β2 pathway." (PMID 32238837, 2020). "Myocardial loss of both IRS1 and IRS2 renders the heart more vulnerable to cardiac dysfunction in mice suffering from diabetes." (PMID 32223896, 2020). "Only a rare heterozygous missense mutation in the last five candidate genes with predicted damaging effects in IRS1 (rs1043152329) was cosegregated with diabetes, which is highly conserved across multiple species." (PMID 32411229, 2020). "In a cohort of AD and diabetes mellitus, the ratio of phospho-serine 312-IRS-1 to pan-phospho-tyrosine-IRS-1 in neuronal EVs from plasma was found to discriminate AD cases from diabetic and control individuals." (PMID 33362690, 2020). "In summary, diabetes inhibited insulin/IRS1/Akt signalling in podocytes, resulting in podocyte apoptosis." (PMID 32238837, 2020). "NGF-driven re-activation of the insulin pathway through disinhibition and tyrosine phosphorylation of IRS1, a primary gatekeeper in insulin signaling, is a potential novel strategy to slow cognitive decline in AD and diabetes-related brain insulin resistance." (PMID 29736736, 2019). "In the current study, we determined the association of the variants of IRS-1 Gly972Arg (G972R) and IRS-2 Gly972Arg (G72R) with diabetes." (PMID 31404179, 2019). "Upregulated C1-Ten seems to accelerate diabetes-mediated pathological features including muscle atrophy and podocyte hypertrophy by affecting IRS-1 in muscle but nephrin in podocytes." (PMID 28955049, 2017). "Our analysis showed that PGRMC1 and HADH genes were significant over diabetes studies, while IRS1 and MPST genes were significant over insulin response studies, and joint analysis showed that HADH and MPST genes were significant over all combined data sets." (PMID 28117714, 2017).
diabetes (continued). "Activating AMP-activated protein kinase (AMPK) is an effective approach for treating diabetes, and reduced insulin receptor substrate-1 (IRS-1) protein levels have been suggested as a molecular mechanism causing insulin resistance." (PMID 29259227, 2017). "The meta-analysis results showed that the PGRMC1 were significant across diabetes studies, presenting six out of 13 studies with the U-score ≤ 0.05, and the IRS1 gene was significant in four studies of insulin response (i.e., U-score ≤ 0.05)." (PMID 28117714, 2017). "It is reported that there is a relationship between TNF-α increase in diabetes and impairment of insulin signaling pathway by increasing serine phosphorylation of IRS-1 which inhibits IR tyrosine kinase activity and leads to downstream signaling." (PMID 27579151, 2016). "We investigated the possible association between insulin receptor substrate-1 (IRS-1) polymorphisms and high platelet reactivity in coronary artery disease (CAD) patients with type 2 diabetes mellitus (T2DM)." (PMID 27005817, 2016). "Liver-specific p85α knockout also increased insulin sensitivity, while p85α haploinsufficiency protected mice with concomitant heterozygous knockout of the insulin receptor and Irs1 from overt diabetes." (PMID 27766312, 2016). "We observed the main effect of diabetes for phosphor-IRS-1 (P = 0.0001) and the abundance of protein was significantly increased by 145% (P = 0.0001) in the gastrocnemius muscle of db/dbCON mice relative to that of db/+CON mice." (PMID 27512375, 2016). "Activation of stress-sensitive kinases like p38 and ERK 1⁄2 stimulates the serine phosphorylation of 1RS-1/IRS-2 which reduces insulin-stimulated IRS-1 tyrosine phosphorylation and insulin sensitivity which triggers the early onset of diabetes." (PMID 26839808, 2015). "Although to date no O-glycosylated residue is mapped on IRS-2, experimental data showed that IRS-2 also have potential to be glycosylated as IRS-1 and this glycosylation was shown to be reduced in diabetes and AD." (PMID 25580119, 2014). "TZQ-F prevents pre-diabetes through increasing effect on IRS-1-dependent PI3K/AKT signaling pathway in muscle." (PMID 24952587, 2014). "Here we propose that alternative O-glycosylation on Ser-312 at N-terminal and Ser-984, Ser-1037, and Ser-1101 at C-terminal of IRS-1 is an important modification that becomes reduced in diabetes and AD due to impaired glucose metabolism." (PMID 25580119, 2014). "It has been previously reported that hepatic Irs1 and Irs2 play a crucial role in glucose homeostasis because simultaneous deletions of both genes in the liver (IrsLDKO) lead to diabetes in mice." (PMID 23940800, 2013). "Based on the literature on other cell types, with the onset of diabetes, TNFα preferentially phosphorylates Ser307 on IRS-1." (PMID 22328823, 2012). "Inhibition or genetic deletion of mTOR or S6K1 in mouse embryonic fibroblasts or breast cancer, but also in murine diabetes models resulted in Ras-MAPK activation via insulin receptor substrate-1 (IRS)." (PMID 22110663, 2011). "(i) Decreased concentration of phosphorylated insulin receptor and IRS-1 are observed in muscle from morbidly obese subjects and those with diabetes." (PMID 15291972, 2004). "Furthermore, it was found that the anti-apoptotic impact of liraglutide on the pancreas and INS-1 cells of diabetes rats was related to the inhibition of miR-139-5p/IRS1 expression." (PMID 40232847, 2025). "That leptin-peptide, leptin-1 activates IRS1 which plays crucial roles in glucose metabolism, signifies that this peptide could exert positive effects on diabetes." (PMID 39490585, 2024). "Since the glucose metabolism plays a critical role in diabetes, and Treg cells regulate inflammatory conditions in adipose tissues, it is reasonable to speculate that IRS1 may play a role in regulating Treg cell function under diabetic conditions." (PMID 36768873, 2023).
diabetes (continued). "Therefore, it can be concluded that the extract plays a role in ameliorating the symptoms of diabetes by modulating the IRS-1/PI3K/AKT signaling pathway and promoting the entry of Nrf2 into the nucleus." (PMID 37764863, 2023). "Thus, the roles of IRS1 in adipose tissue Treg cells, and in the development of diabetes, warrant further study." (PMID 36768873, 2023). "To conclude, our study identifies the lncRNA H19 as a critical determiner of cellular IRS1 levels and during diabetes, decreased levels of this lncRNA promotes an inhibition in IRS1 gene expression, possibly due to increased deacetylation mediated by HDAC6 in the skeletal muscle." (PMID 35842608, 2022). "S. tamariscina, in particular, has been reported to possess antioxidant, anti-hyperglycemic, and antihyperlipidemic effects in diabetes by enhancing peroxisome proliferator-activated receptor gamma (PPARγ) expression in AT and insulin receptor substrate 1 (IRS-1) expression in liver and muscle." (PMID 35454963, 2022). "Diabetes suppressed Cdk4 and Irs1 gene expression that was elevated by GQD and metformin indicated these two genes might be the key targets for α-cell proliferation." (PMID 35858880, 2022). "Here, we have demonstrated that the reduced IR and IRS1 protein levels are attributable to not only the increased expression of MG53 but also the elevated phosphorylation at S255 by GSK3β in the context of diabetes." (PMID 36337049, 2022). "Diabetes onset also perturbed β-cell function and insulin resistance indices, damaged pancreas microanatomy, while disrupting the expression of insulin receptor substrate 1 (IRS-1), phosphatidylinositol 3-kinase (PI3K), protein kinase B (AKT) and glucose transporter isoform 4 (GLUT-4) mRNA." (PMID 35739183, 2022). "Altogether, animal and cell culture data showed a potential role of TP63 as a new candidate gene involved in regulating IRS-1 that may be used as a new therapeutic target to prevent kidney complications in diabetes." (PMID 33920782, 2021). "And the brain IR/IRS-1 signaling pathway plays an important role in astrocyte-neuron metabolic coupling, providing a potential mechanism by which the IR/IRS-1 signaling pathway may contribute to the treatment of ZJJ on diabetes-related depression." (PMID 34149862, 2021). "A crosstalk between insulin and Igf-1 is mediated by the phosphorylation of Irs1 residues; thus, insulin/IGF-1 signaling could underlie the poor healing of injured muscles that is associated with diabetes." (PMID 33803124, 2021). "It is also well-known that a loss of IRS-1 does not directly result in diabetes, owing to a robust compensatory mechanism among the different IRS subtypes." (PMID 33240103, 2020). "Additionally, ABA reduced plasma levels of leptin and resistin, two notable adipokines tied to the diminished uptake of glucose in diabetes and impaired IRS-1 signaling." (PMID 32591558, 2020). "For instance, microRNA 144 could repress insulin signaling during type 2 diabetes mellitus development through suppressing the expression of Insulin Receptor Substrate 1 (IRS1)." (PMID 32258168, 2020). "In a study on GDM, the frequency of IRS-1 gene polymorphism was significantly higher in women with GDM than in pregnant women with a normal glucose tolerance, suggesting a role for this polymorphism in the onset of GDM as well as type 2 diabetes mellitus." (PMID 33335512, 2020). "Additionally, HFD- and STZ-induced diabetes increases the phosphorylation of JNK accompanied by the activation of mSer307 on IRS1 in the brain." (PMID 31426549, 2019). "Therefore, the proposed role for MG53 mediated IRS-1 downregulation in the manifestation of diabetes lacks a biological base." (PMID 31604915, 2019). "The decreased hepatic expression of IRS1 and β-catenin in NAFLD is linked to histological progression such as ballooning, and might lead to diabetes as a result of impaired glucose metabolism." (PMID 29749571, 2018).
diabetes (continued). "The IRS1 also showed a small U-score of 0.003% in the diabetes study 4 of blood." (PMID 28117714, 2017). "Increase in IRS1 in HFD-fed rats by MZ suggests a protective role in diabetes." (PMID 28804442, 2017). "In view of the crucial role of IRS-1 in insulin signaling, polymorphisms in the IRS1 gene were considered to have an impact on IRS-1 function and association with diabetes, especially those nonsynonymous mutations." (PMID 25978640, 2015). "At 3 months, fructose feeding induced upregulation of several genes coding nuclear factors (Rxrg, Nr1h3, p≤0.1), proteins involved in lipid metabolism including Pltp (p≤0.1), Lcat, and Cd36 (p≤0.05), cell death inflammation (Tnf, p≤0.1), and diabetes (Irs1, Slc2a2, p≤0.1)." (PMID 25380250, 2014). "The proposed extracellular model of Cr(III) action in this report is upstream of IRS1, a therapeutic target of White and others, and may lend itself to small-molecule therapeutic strategies for diabetes and other metabolic conditions." (PMID 15603587, 2004). "The insulin and insulin-like growth factor 1 (IGF-1) receptor, insulin receptor substrates 1 and 2 (IRS1/2), and important second messenger kinases like Akt and mTOR were all found to be inactivated in patient brain tissue, which is comparable to what is seen peripherally in diabetes." (PMID 40964464, 2025). "monnieri may minimize the signs and symptoms of diabetes via enhancing IRS1/AKT signaling." (PMID 38380214, 2024). "Consequently, IR/IRS-1 signaling in the astrocyte may involve in the comorbid depression in diabetes." (PMID 34149862, 2021). "Interestingly, most transcripts namely, Pck2, Prkab2, Pik3r1, Foxo1, Irs1 and Pik3r5 are commonly involved in these pathways and this suggests a significant involvement and contribution of these genes in aberrant skeletal muscle metabolism during diabetes." (PMID 34190986, 2021). "However, considering diabetes may affect the p-IRS-1 in the neurons, people with diabetes in both control and PD group were separated into individual subgroup." (PMID 33344443, 2020). "Notably, IRS1 is dysregulated in hearts and other tissues in diabetes." (PMID 32223896, 2020). "This study was conducted to reveal the relationship between diabetes-induced oxidative stress and tissue inflammation with changes in main enzymatic antioxidants (cat, sod, gpx, and gst) and the components of the insulin signaling pathway (insulin Rβ, irs-1, pi3k, akt, mtor) in kidney tissues." (PMID 30602713, 2018). "Interestingly, icv injections of Aβ oligomers in mice provokes peripheral glucose intolerance, insulin resistance, and inflammation characterized by activation of JNK and IKK and IRS-1 inhibition, connecting AD pathology progression to the development of diabetes." (PMID 30542257, 2018). "This latter finding could be important in the context of previous studies in cancer or diabetes model systems, which indicated that NE liberated from infiltrating neutrophils enters surrounding cells, altering cell signaling by the degradation of IRS1." (PMID 28659928, 2017). "Recent study showed that increased insulin receptor substrate 1 (IRS1)-phosphoinositide 3-kinase (PI3K) activity with a concurrent activation of the insulin receptor was occurred with a diminished translocation of GLUT4 to the sarcolemmal membrane in the heart even in fasting status of diabetes." (PMID 26538247, 2015). "They reported that the p.His713Tyr variant might result in defective binding to PI3K, which leads to an IRS1-associated reduction in PI3K activity and subsequent activation of Akt, ultimately affecting insulin signaling to the cellular carrier pathway and thereby causing diabetes." (PMID 40747301, 2025). "IRS1 and IRS2 in the insulin signaling pathway are dysregulated in diabetes mellitus, so they need to work in concert to maintain normal glucose metabolism and insulin sensitivity." (PMID 40747301, 2025).
diabetes (continued). "PyRx and HDOCK servers were used in diabetes molecular docking to determine the effect of stevioside against GLUT-4, Akt, IR, and IRS-1 proteins." (PMID 39170696, 2024). "Further quantitative expression of mRNA of diabetic candidate genes like, IRS-1, GLUT-4, SIRT 1 and ADAM17 were also studied for their role on the part of protective potential of B. brandisiana and berbamine in diabetes." (PMID 37089941, 2023). "The current study found a significant downregulation of insulin receptor, IRS-1, and IRS-3 genes expression in skeletal muscles with induced diabetes while treatment with either telmisartan or metformin significantly enhanced their expression." (PMID 37576807, 2023). "We conclude that the synthesized nanoparticles are more powerful in reducing the hyperglycemia and enhances the IRS1 and AMPK expression for treatment of diabetes, which aid in glucose uptake and insulin sensitization." (PMID 35956652, 2022). "In the present study, women with diabetes in both groups had a low-levelexpression of INSR and IRS-1 genes compared to healthysubjects." (PMID 36273315, 2022). "After pooling the screened targets of diabetes and cell proliferation from GQD and metformin, the PPI network showed a linear interaction from CDK4 to IRS1." (PMID 35858880, 2022). "As previous studies indicated, miR-146a-5p could inhibit diabetes-induced defects in retinal endothelial cells via targeting several key molecules of the NF-κB pathway, and miR-7-5p could reduce proliferation of retinal endothelial cells through targeting IRS1 and deactivating the PI3K/AKT pathway." (PMID 33898104, 2021). "GCG, IRS1, VEGFA, STAT3, CCL2, CASP3, and APOE as diabetes mellitus-related proteins and SREBF1, LPL, PPARA, APOB, GPT, MAPK8, and FASN as NAFLD-specific proteins were identified as possible discriminating factors between the two studied diseases." (PMID 35154608, 2021). "Modulation on several proteins, including HOMA-β, HOMA-IR, Glucagon-like peptide-1 (GLP-1), insulin receptor substrate 1 (IRS-1), phosphoinositide 3-kinase (PI3K), and Akt are reported on diabetes with suppression of apoptosis on pancreatic cells." (PMID 35155528, 2021). "These proteins are important insulin pathway-related factors, and the deletion of IRS1 and IRS2 genes leads to the development of diabetes in mice." (PMID 34497509, 2021). "While IRS1 expression and phosphorylation are normal or reduced, IRS2 has normal levels in diabetes models." (PMID 32377524, 2020). "In the current study, we have investigated the mRNA levels of insulin receptor substrate 1 (IRS-1), PI3K, Akt-2, and GLUT-4 and GLUT4 protein in skeletal muscle of normal control, diabetes control and treatment groups." (PMID 32987623, 2020). "The expression of IRS-1 and IRS-2 were also increased in muscle from diabetes group when compared with control group." (PMID 33203103, 2020). "The individuals with non-insulin dependent diabetes mellitus (NIDDM) have decreased expression and function of IRS-1 in the fat cells." (PMID 31404179, 2019). "Further, diabetes with CUMS exhibited a significant decrease in phosphorylation of insulin receptor and an increase phosphorylation of IRS-1 in brain." (PMID 30622594, 2018). "Thus, dual targeting of AMPK and IRS-1 might provide an ideal way to treat diabetes." (PMID 29259227, 2017). "Consistent with our results, it has been demonstrated that deletion of IRS1 and IRS2 genes in mice prevented activation of liver Akt-Foxo1 phosphorylation and led to the development of diabetes." (PMID 29207597, 2017). "The PAD gene list relates to a diverse set of human diseases, including cardiovascular (LMNA, MYH7), cystic fibrosis (CFTR), diabetes (HNF4A, IRS1) and migraine (ATP1A2)." (PMID 25611800, 2015).